TLR4 (toll like receptor 4)
Diseases named in the same sentence as TLR4 in open-access papers (continued):
Sharing a sentence is not in itself a finding about the gene and the disease.
periodontitis (continued). "As TLR4 and CD14 were previously associated with LPS hyporesponsiveness and RANKL and OPG to the regulation of bone mass, we hypothesized that the polymorphisms in the genes that codified these proteins could influence the pathogenesis of periodontitis." (PMID 31281226, 2019). "Therefore, we hypothesized that MB could target macrophages by binding to LPS, which makes contact with TLR4 in macrophages when periodontitis develops." (PMID 31485288, 2019). "Therefore, this case-control study was conducted to evaluate the possible influence of immune innate and bone resorption gene polymorphisms, TLR4, CD14, RANKL, and OPG, in periodontitis, in carefully selected patients and controls based on clinical parameters and especially in nonsmokers." (PMID 31281226, 2019). "Interestingly, we observed that much like the primary human gingival epithelial cells, stimulation of epithelial cells in periodontitis saliva with TLR-2 or TLR-4 specific ligands induced cytokine secretion with differential kinetics and up-regulated TLR-2 and TLR-4 mRNAs." (PMID 30571680, 2018). "However, the influence of TLR4 or NF-κB blockage in vivo on the pathogenesis of periodontitis is still unknown." (PMID 24887697, 2014). "Blockage of TLR4 or NF-κB pathway might provide a new approach for periodontitis treatment." (PMID 24887697, 2014). "Toll-like receptor 4 (TLR4) is described as the receptor of S100A9, so we further explored the transformation of TLR4 signaling way in the model of high-sugar-induced periodontitis." (PMID 40173189, 2025). "In contrast to the healthy group, the periodontitis group had higher levels of ENTPD1, TLR4, LY96, and PRF1 expression and lower levels of P2RX7 expression, according to the qPCR data." (PMID 39555084, 2024). "In line with the findings of the validation set, our findings demonstrated that ENTPD1, TLR4, LY96, PRF1 were elevated in periodontitis patients while P2RX7 expression was decreased." (PMID 39555084, 2024). "Increased expression levels of PTCSC3 can improve periodontitis by inhibiting PDLSC levels and reducing TLR4 levels." (PMID 39063437, 2024). "Periodontitis-affected PDLSC proliferation was suppressed by overexpression of PTCSC3, which also resulted in the downregulation of TLR4." (PMID 39063437, 2024). "In a study related to periodontitis, SIRT1 was reported to alleviate LPS-induced inflammation of human periodontal ligament fibroblasts (HPDLFs) through the downregulation of Toll-like receptor 4 (TLR 4)." (PMID 38790655, 2024). "In established chronic periodontitis mouse model, NAC‐S2 attenuated inflammatory response in TLR4/Myd88‐depedent manner." (PMID 37647428, 2023). "Interestingly, we found that TLR4 overexpression could reversed the effects of circ_0099630 knockdown and recovered LPS-induced injuries in HPDLCs, confirming that TLR4 might be a potential target for periodontitis treatment." (PMID 38007427, 2023). "In periodontitis, increased levels of the pro-inflammatory cytokines IL-1 and TNF-a are observed, and the expression of TLR-2 and TLR-4 expression is increased." (PMID 36013115, 2022). "The binding of LPS to TLR4 increases MMP and proinflammatory cytokine expression via various signaling pathways such as IRAK, TAK, and NF-κB during the development of periodontitis." (PMID 36246974, 2022). "In both Tlr2 and Tlr4 KO models, the expression of RANKL mRNA in the gingival tissue of ligation-induced experimental periodontitis was still significantly higher than that in the control group." (PMID 34445604, 2021). "And indeed, in a variety of case-control studies as well as in meta-analyses, their impact on periodontitis as well as CV diseases was assessed (CD14, NF-κΒ, TLR2, and TLR4)." (PMID 34305452, 2021). "Finally, we suggest that S100A9-RAGE and -TLR4 pathways in osteocytes may be potential targets for the therapy against bone destruction mediated by the host immune and inflammatory responses to the microbial challenge, such as periodontitis." (PMID 32149126, 2020).
periodontitis (continued). "It is known that TLR-4 and TLR-2 expression levels are highly increased in periodontitis lesions, compared to healthy periodontal ligament." (PMID 32714091, 2020). "Several periodontopathogens have been identified, of which Pg is one of the bacteria in the initiation and progression of periodontitis and which interacts either via TLR2 or TLR4." (PMID 31817424, 2019). "Therefore, TLR4 may participate in periodontitis through PDLSCs proliferation-independent pathways." (PMID 31196168, 2019). "Intracellular expression of TLR-4 and TLR-2 was confirmed by recent report concerning immunohistochemical detection of them in pocket epithelial cells in periodontitis." (PMID 30165815, 2018). "The expression of Toll-like receptor 2 (TLR2), TLR4, TNF-α, and inducible NO synthase was mainly detected in the gingival macrophages of chronic periodontitis patients." (PMID 24363500, 2013). "In the present study, we confirmed that macrophages densely expressed TLR2, TLR4, TNF-α, and iNOS in the gingival tissues of chronic periodontitis patients." (PMID 24363500, 2013). "Interactions between HtpG and the TLR4 and CD91 receptors induce the chemokine CXCL8, a chemoattractant for phagocytic cells in periodontitis and thus perpetuating the uncontrolled inflammation characteristic of periodontitis." (PMID 18431474, 2008). "Amongst the PAMPs present in F. nucleatum, lipopolysaccharide (LPS), an outer membrane component of gram‐negative bacteria, is a strong instigator of TLR‐4 mediated immune responses contributing to the inflammatory changes of periodontitis." (PMID 40708487, 2025). "Genotypic and allelic frequencies of polymorphisms A-2570G (rs2737190), A896G (rs4986790), and C1196T (rs4986791) of the TLR4 gene in individuals with and without periodontitis." (PMID 40552316, 2025). "Significant changes in plasma and salivary TLR2 and TLR4 levels have been reported in individuals with chronic periodontitis (CP); however, to the authors' knowledge, there is no systematic review analyzing these results." (PMID 40371381, 2025). "LPS injection elicits a robust, largely Toll-like receptor 4-driven, non-specific response, whereas periodontitis is predominantly T cell-mediated." (PMID 41440335, 2025). "PTCSC3 was significantly downregulated, and TLR4 was significantly upregulated in PDLSCs from the teeth of individuals with periodontitis, respectively, but not from the teeth of healthy subjects." (PMID 39063437, 2024). "TLR2 and TLR4 are involved in the immune response against bacterial pathogens (both Gram-positive and Gram-negative bacteria) in cariogenesis and in periodontitis." (PMID 39000094, 2024). "In the process of developing periodontitis, LPS, a component of Gram-negative bacteria, reacts with Toll-like receptor 4 (TLR 4), a membrane protein of host cells, and activates inflammatory pathways such as NF-ĸB into cells." (PMID 38790655, 2024). "TLR4 was formerly proved to mediate the activation of proinflammatory cytokines and play a negative role in periodontitis pathogenesis." (PMID 38279054, 2024). "Besides, we screened miR-409-3p and proposed the circ_0099630/miR-409-3p/TLR4 network to illustrate the functional mechanism of circ_0099630 in LPS-mediated HPDLC injuries, aiming to provide additional opinion for periodontitis treatment." (PMID 38007427, 2023). "More importantly, NAC‐S2 treatment shows no influence on CEJ to ABC distance in TLR4‐/‐ or Myd88‐/‐ mice periodontitis model." (PMID 37647428, 2023). "Our study demonstrates that NAC‐S2 could suppress the Toll‐like receptor 4 (TLR4)/Myd88‐dependent NF‐κB and IκB kinase (IKK) signaling pathways in periodontitis." (PMID 37647428, 2023). "Melatonin decreases the production of pro-inflammatory mediators via TLR4/myeloid differentiation factor 88 (TLR4/MyD88) pathway and further rebalances RANKL/OPG/RANK system, ameliorating inflammatory alveolar bone resorption in rats with experimental periodontitis." (PMID 36359775, 2022).
periodontitis (continued). "M1 macrophages regulate TLR4/AP1 and promote alveolar bone destruction in periodontitis." (PMID 36045361, 2022). "In a study on HIV-positive North American patients with periodontitis, 8 SNPs in 6 TLR genes (TLR1 (n = 2), TLR2 (n = 1), TLR4 (n = 1), TLR6 (n = 1), TLR8 (n = 2), and TLR9 (n = 1)) were positively associated with P. gingivalis (2 SNPs), T. denticola (6 SNPs), and T. forsythia (1 SNP)." (PMID 35122548, 2022). "Based on the data available, we assessed in our study the impact of SNPs in TLR2 (rs5743708), TLR4 (rs4986790), CD14 (rs2569190), and NF-κΒ (rs28362491), on severe periodontitis as well as on the incidence of new CV events within a three year follow-up in a cohort of CV patients." (PMID 34305452, 2021). "Among them, TLR2, TLR4, and TLR9 play important roles in the development of periodontitis." (PMID 34445604, 2021). "LPS, a well-known microbe-associated molecular pattern (MAMP) derived from Gram-negative bacteria in periodontitis, is a major cell-wall component of Gram-negative bacteria and identified as a ligand for TLR4." (PMID 34172796, 2021). "Previously, it was reported that RAGE levels were elevated in patients susceptible to periodontitis compared to healthy patients, but TLR2 and TLR4 levels did not change before implant therapy." (PMID 32760399, 2020). "In periodontitis an abnormal immune response known as a “hyper-responsive” phenotype was demonstrated by investigations of peripheral blood leukocytes that were stimulated with TLR2 and TLR4 agonists." (PMID 30837987, 2019). "PTCSC3 overexpression led to the downregulation of TLR4 in PDLSCs isolated from periodontitis affected teeth, while TLR4 overexpression failed to significantly affect PTCSC3." (PMID 31196168, 2019). "Comparing to healthy PDLSCs, PTCSC3 was significantly downregulated, while TLR4 mRNA was significantly upregulated in periodontitis-affected PDLSCs (p < 0.05), indicating the involvement of PTCSC3 and TLR4 in the pathogenesis of periodontitis." (PMID 31196168, 2019). "GFs could secrete IL-6 and CCL2 via activating TLR4 signaling, MAPK, and NF-κB pathways, resulting in the progression of periodontitis." (PMID 31608279, 2019). "In order to mimic an enduring bacterial pressure, as is the case during chronic periodontitis, TLR2, TLR4, or a combination of both agonists, were added to the PBMC/PBL cultures and GF cocultures for 21 days, where after the effects on leukocyte survival and selective proliferation were assessed." (PMID 31817424, 2019). "In conclusion, PTCSC3 was downregulated in periodontitis, and overexpression of PTCSC3 may improve periodontitis by inhibiting the proliferation of PDLSCs and downregulating TLR4." (PMID 31196168, 2019). "Expression levels of PTCSC3 and TLR4 were only significantly and inversely correlated in PDLSCs isolated from periodontitis affected teeth but not in PDLSCs isolated from healthy teeth." (PMID 31196168, 2019). "Although the mechanism through which P. gingivalis-induces bone resorption via TLR2 and TLR4 is not fully understood, our results suggest that TLR-stimulation in periodontitis upregulates alveolar bone resorption under high plasma concentration of oxLDL in dyslipidemia." (PMID 29859535, 2018). "According to the present study, it was concluded that IL-36γ increased in periodontitis, which could stimulate MAPK and TLR4 pathways." (PMID 30443300, 2018). "As opposed to this, in periodontitis saliva, the sTLR-4 concentration exhibited a moderate inverse correlation with the paired SEC associated TLR-4 mRNA level (r2 = 0.4)." (PMID 30571680, 2018). "Binding of TLR2 and TLR4 to PAMPs presented on pathogens will induce the expression of ICAM-1 and LFA-1 in the oral cavity which can lead to downstream bone resorption and increase in the rate of periodontitis." (PMID 28326084, 2017).
periodontitis (continued). "Since the primary etiological factor of periodontitis is predominantly gram negative bacteria and/or LPS, TLR4 expression by macrophages is critical in mediating host inflammatory responses in the gingiva by binding LPS." (PMID 26317345, 2015). "Alternatively, liver Kupffer cells (liver resident/tissue macrophages) in mice with TLR4 LOF do not respond to LPS originating from periodontitis sites so that the TLR4-induced cytokine response in the liver is blocked." (PMID 26317345, 2015). "TLR4 recognizes LPS from gram-negative bacteria, which are the most important factor involved in periodontitis." (PMID 24887697, 2014). "Nevertheless, there are no reports on the role of miR-511/TLR4 in periodontitis." (PMID 33679417, 2021). "Moreover, TRIM52 knockdown could mitigate LPS-induced elevation of TLR4 expression, revealing that TLR4 is involved in the impact of TRIM52 on LPS-induced inflammatory injury during periodontitis." (PMID 32735017, 2020). "Also, receptors such as TLR-4 and TLR-2 are connected to the pathology of periodontitis." (PMID 33093521, 2020). "It is worth noting that certain pathological mediators may exist between PTCSC3 and TLR4 due to the fact that expression levels of PTCSC3 and TLR4 were only significantly correlated in periodontitis-affected PDLSCs, but not in healthy PDLSCs." (PMID 31196168, 2019). "However, it has never been demonstrated that aCL found in sera from periodontitis patients can interact with and activate TLR4." (PMID 30192824, 2018). "In this study, allele and genotype frequency distributions of TLR4 A896G (rs4986790), TLR4 C1196T (rs4986791), CD14 C-260T (rs2569190), RANKL (rs2277438), and OPG C163T (rs3102735) polymorphisms were analyzed in a total of 203 patients with periodontitis and 213 subjects without the disease." (PMID 31281226, 2019). "However, TLR4 failed to significantly affect the proliferation of periodontitis-affected PDLSCs." (PMID 31196168, 2019). "However, TLR4, RANKL, and OPG polymorphisms could be a risk for periodontitis in males regardless of smoking habits." (PMID 31281226, 2019). "In wild‐type periodontitis mice, NAC‐S2 administration decreased the cemento‐enamel‐junction–alveolar bone crest (CEJ‐ABC) distance and the relative mRNA expression of TNF, IL‐6, and IL‐1β, while such phenomena could not be observed in TLR4 deficiency or Myd88 deficiency mice." (PMID 37647428, 2023). "We purified IgG from 16 subjects with elevated or normal levels of aCL and examined their ability to activate TLR2- or TLR4-transfected human embryonic kidney (HEK) cells, and observed that IgG from periodontitis patients with elevated aCL activated HEK-TLR4 cells, but not HEK-TLR2 cells." (PMID 30192824, 2018). "Finally, genotypes are described that protect the mice from periodontitis: the SCID mouse, and mice lacking Tlr2/Tlr4, the Ccr1/Ccr5, the Tnf-α receptor p55, and Cathepsin K by attenuating the inflammatory reaction and the osteoclastogenic response." (PMID 29163477, 2017). "To test our hypothesis, we collected periodontal tissues from patients with or without periodontitis and T2DM at the time of necessary surgeries and determined the mRNA expression of TLR4, CD14, MD-2 and MyD88 using quantitative real-time polymerase chain reaction (PCR)." (PMID 26581717, 2015). "However, if the primary trigger is circulating LPS, then GFPWT:WT chimeras with periodontitis will develop impaired GI/IR, but the GFPWT:KO chimeras with periodontitis will not, as the liver tissue resident macrophages (primarily Kupffer cells) in these animals do not express TLR4." (PMID 26317345, 2015).
ischemic stroke (132 papers, 2013 to 2026). A stroke disorder caused by obstruction of blood flow to the brain, due to thrombotic (local blood clot formation) or embolic (due to a blood clot or other material traveling from another site) event. "We show that eCIRP causes microglial efferocytic dysfunction in ischemic stroke via TLR4/miR-155/MafB axis." (PMID 40766256, 2025). "Considering the cause-and-effect relationship between ischemic stroke and traumatic brain injury, it is apparent that TLR4 is a potential therapeutic target for CI/R injury treatment." (PMID 36879557, 2023). "Studies have demonstrated that TLR4 plays an important role in the innate immunity response of the central nervous system, and participates in cerebral damage caused by ischemic strokes." (PMID 37904689, 2023). "The expression and diagnostic value of MAP1LC3B, PTGS2, and TLR4 in ischemic stroke were also verified using GSE22255." (PMID 34707562, 2021). "All in all, our results suggested MAP1LC3B, PTGS2, and TLR4 as potential diagnostic biomarkers for ischemic stroke, providing more evidence about the vital role of ferroptosis in ischemic stroke." (PMID 34707562, 2021). "TLR4-knockout mice show indeed smaller infarct sizes and improved neurological deficits after stroke, and in humans, TLR4 polymorphisms have been associated with ischemic stroke outcome." (PMID 30584250, 2018). "Increased TLR4 expression is associated with a poor prognosis in mice with ischemic stroke." (PMID 36979506, 2023). "TLR4 is a central gene involved in ferroptosis associated with ischemic stroke." (PMID 38049739, 2023). "Elevated TLR4 protein levels are associated with poor outcomes in patients with ischemic stroke." (PMID 35055089, 2022). "Moreover, the ROC diagnostic accuracy of MAP1LC3B, PTGS2, and TLR4 was 71.75, 68.26, and 53.25%, respectively, further confirming the diagnostic value of three ferroptosis-related biomarkers in ischemic stroke." (PMID 34707562, 2021). "Another bioinformatic study revealed that TLR4 may be implicated in atrial fibrillation, a risk factor for ischemic stroke." (PMID 34707562, 2021). "Many studies have focused on the role of TLR2 and TLR4 in brain damage caused by ischemic stroke." (PMID 32746852, 2020). "Clinical studies found that TLR4 polymorphisms were associated with ischemic stroke outcome, and TLR4 expression was independently associated with lesion volume and correlated with the intense inflammatory response after ischemic stroke." (PMID 27716839, 2016). "Furthermore, TLR4 signaling is also involved in brain damage and in neuroinflammatory processes associated with ischemic stroke and neurodegenerative diseases, such as Alzheimer's disease." (PMID 24223475, 2013). "MD2 is a pivotal regulator of neuroinflammation and neuronal death in ischemic stroke, acting through both TLR4-dependent and independent pathways." (PMID 40723833, 2025). "The neuroprotective mechanisms are associated with regulations of TLR4/NF-κB/NLRP3/ caspase-1 and caspase-3 signals, as well as Bcl-2/Bax ratio, suggesting SO is a novel neuroinflammatory regulator in ischemic stroke." (PMID 40289983, 2025). "Previous research has revealed that after ischemic stroke, activated the signaling pathway of TLR4/MyD88/NF-κB increases the production of inflammatory mediators." (PMID 39962509, 2025). "Casp3, a key executor of apoptosis, has been shown to mediate cell death in ischemic stroke, while Il1b and Tlr4 are pivotal in initiating and propagating inflammatory responses." (PMID 40002863, 2025). "Twelve genes have been reported as potential regulators of HT in ischemic stroke in previous studies: Casp3, Csf2, Ctnnb1, Cxcl12, Hif1a, Il1b, Mtor, Ptgs2, Ptprc, Tlr2, Tlr4, and Vcam1." (PMID 40002863, 2025). "The two-way factorial ANOVA analysis revealed that ischemic stroke significantly affected Tlr4 expression." (PMID 40867143, 2025).